GLI1 (GLI family zinc finger 1)
Diseases named in the same sentence as GLI1 in open-access papers (continued):
Sharing a sentence is not in itself a finding about the gene and the disease.
breast carcinoma (continued). "We examined the endogenous mRNA expression of breast cancer stem cell markers ALDH1, Gli1 and ER in several human breast cancer cell lines using real-time polymerase chain reaction (PCR)." (PMID 24889938, 2014). "High GLI1 expression is a property of claudin-low cells and tumors and correlates with markers of EMT and breast cancer stem cells." (PMID 25252859, 2014). "Consistent with the results derived from cell line studies, the expression of the Hh signaling molecules (Shh, GLI1, Smo, Sufu) was found to be negatively correlated with LKB1 expression in human breast cancer specimens." (PMID 23861764, 2013). "In this study, we observed that activated LKB1 decreased the expression of factors related to Hh reporter activity in MDA-MB-231 breast cancer cells, including of SMO, SHH and GLI1." (PMID 23861764, 2013). "In the context of drug resistance and breast tumor recurrence, Smoothened and Gli1 were reported to be significantly upregulated in tamoxifen-resistant derivative of otherwise tamoxifen-sensitive MCF-7 and T47D breast cancer cells." (PMID 23533807, 2013). "We have determined that breast cancer cells express elevated staining intensities for the Hh ligand IHH and the transcription factor, GLI1, indicating that the Hh pathway is activated in breast tumor cells." (PMID 22479615, 2012). "Additionally, targeting GLI1 as a key gene may facilitate the screening of effective therapeutic agents, contributing to the advancement of personalized treatment approaches for breast cancer and promoting relevant clinical trials for combination immunotherapy." (PMID 39483334, 2024). "In various cancer models—breast cancer cells, gastric cancer cells, medulloblastoma —CUR has been shown to inhibit the Hh pathway by downregulating the expression of SHh, PTCH1, and GLI1/GLI2." (PMID 39457084, 2024). "mRNAs of SHH, PTCH1, and GLI1 are highly expressed in breast tumors, inspiring the hypothesis that the SHH pathway may help predict postoperative relapse in breast cancer patients." (PMID 36017236, 2022). "The ability of the Wnt pathway to promote GLI1, and potentially tGLI1, activation in combination with the limited efficacy of SMO inhibitors in breast cancer clinical trials provides the rationale for directly targeting tGLI1 as a potential therapeutic modality." (PMID 36077791, 2022). "Therefore, we used the Kaplan–Meier plotter website to analyze the effects of SHH, PTCH1, SMO, GLI1, and GLI2 on the prognosis of breast cancer patients." (PMID 36142286, 2022). "Furthermore, the Hedgehog-Gli1 signaling pathway, which when blocked, lowers stem cell survival by reducing the proteins SMO and/or Gli1, has been found to be dysregulated in breast cancer stem cells." (PMID 34698063, 2021). "Moreover, GLI1 (GANT61) but not SMO (GDC-0449 and LDE225) inhibition significantly reduced FOXC1-induced GLI-BS-luciferase activity in both SMO-positive and SMO-negative breast cancer cell lines, suggesting an SMO-independent activation of GLI." (PMID 34572373, 2021). "In claudin-low breast cancer and EMT cell lines, the p65 subunit of the NFκB act as a transcriptional regulator of GLI1 expression by binding to the κB binding site located within the GLI1 promoter." (PMID 34572373, 2021). "In ER+ subtype breast cancer, estrogen triggers the overexpression of SHH and GLI1." (PMID 32962123, 2020). "Interestingly, we found that Gli1 was significantly up‐regulated in breast cancer tissues, whereas PTCH1, SMO, Gli1 and HHIP at mRNA and protein levels were all down‐regulated after controlling for EGOT overexpression." (PMID 32150666, 2020). "Moreover, GLI1 also stimulates CXCL12-dependent ERK phosphorylation and migration of breast cancer cells." (PMID 33096815, 2020). "Previous reports also suggest that both GLI1 and ACVR1C are down-regulated in breast cancer." (PMID 31973134, 2020).
breast carcinoma (continued). "Non-canonical GLI1 activation is one mechanism by which estrogen exposure promotes breast cancer stem cell proliferation and epithelial–mesenchymal transition." (PMID 31394751, 2019). "Furthermore, the RNA oligo that effectively competed with GLI1 mRNA-IGF2BP1 interaction was efficient at reducing GLI1 expression in colorectal and breast cancer cells." (PMID 29987229, 2018). "Oncogenic transcription factor Gli1 promotes migration and invasion of ER− breast cancer cells through the up-regulation of MMP11 and reduced MMP11 expression mediates the anti-angiogenic and invasion effect of microRNA miR-98 in ER− breast cancer cells." (PMID 28409241, 2017). "Each EMT-TF positively correlates with GLI1, across multiple breast cancer data sets, but not consistently with Hh ligands." (PMID 28604738, 2017). "Importantly, we demonstrate that in selected patient-derived breast cancer xenograft (PDX) models, GANT61 (a GLI1/2 inhibitor) inhibits tumour growth, whereas IPI926 (a SMO inhibitor) does not." (PMID 28604738, 2017). "It is therefore conceivable that these findings could, ultimately, be exploited not only to identify the response of various breast cancer cell types to TAM, but also to examine whether GLI1 expression may serve as marker of TAM sensitivity and/or resistance." (PMID 26927093, 2016). "Indeed, we observe that high GLI1 expression predicts worse DMFS in Grade 1, ERα-positive breast cancer patients." (PMID 27689403, 2016). "Also in breast cancer, IHH-induced GLI1 activity promoted osteoblast expression of Rank ligand and osteopontin (OPN)." (PMID 26988232, 2016). "Using a panel of different breast cancer cell lines, we demonstrated that TAM modulates the expression of HH signaling components, including the terminal effector of the pathway, the transcription factor GLI1." (PMID 27548161, 2016). "Comprehensive screening of genes down-regulated by TSHZ2 revealed that some, but not all, of these genes were up-regulated by GLI1 in a breast cancer cell line." (PMID 26744317, 2016). "Among these, GLI1 and GLI2 have been thought to be crucial for the development and progression of many types of human cancers, including lung, pancreatic, prostate, and breast cancer." (PMID 26413813, 2015). "These evidences indicated a role of GLI1 in enhancing the CXCL12/CXCR4/CXCR7 signaling axis, which may be responsible for tissue-specific metastasis of breast cancer cells." (PMID 26413813, 2015). "Furthermore, we revealed that GLI1 up-regulated the expression of CXCR4, CXCR7, and LCP1 to enhance the CXCL12-induced ERK phosphorylation and migration of breast cancer cells." (PMID 26413813, 2015). "The increased expression of GLI1 has been reported to clinically correlated with the metastasis and unfavorable overall prognosis of breast cancer, and yet its molecular mechanism has not been explained." (PMID 26413813, 2015). "Using breast cancer cells lines (MCF-7 and HCC1428), we demonstrated that estrogen may act via Gli1 to promote CSC development and EMT in ER-positive breast cancer cells, which may contribute to breast tumor malignancy." (PMID 24889938, 2014). "Studies in non-IBC breast cancer cell lines have suggested a link between ER status, GLI1 levels and survival, and shown that GLI1 silencing in ER negative breast cancer markedly reduces survival and invasiveness." (PMID 21505458, 2011). "Additionally, a pathway that may interact with Hedgehog signalling in breast cancer is TGF-β, which stimulates the upregulation of GLI1 and GLI2 transcription." (PMID 41301715, 2025). "Interestingly, recent studies have shown that CUR inhibits the Hh pathway in several other cancers, such as breast cancer, gastric cancer, and medulloblastoma, by downregulating the expression of SHh, PTCH1, and GLI1/GLI2, leading to reduced cell proliferation, invasion, and migration." (PMID 39457084, 2024).
breast carcinoma (continued). "Additionally, basal expression of GLI1 and GLI2 is higher in triple negative breast cancer (TNBC) than in hormone-receptor (HR) positive breast cancer suggesting this pathway may be especially relevant to this subtype." (PMID 32957513, 2020). "Hh pathway activation may also promote invasiveness of breast cancer cells: GLI1 enhances the invasiveness of HR negative cells by upregulating matrix metallopeptidase 11 (MMP-11)." (PMID 31394751, 2019). "GLI1 is activated through non-canonical pathways in several cancers including breast cancer." (PMID 31394751, 2019). "In addition, basal expression levels of GLI1 and GLI2, which are downstream of Hh ligands, are higher in TNBC than in HR+ breast cancer, suggesting that this pathway may be especially relevant to this sub-type." (PMID 31394751, 2019). "Specifically, the shh-GLI1 pathway is promoted by Hh to induce OCT4 and SOX2 expression in breast cancer cells, which is crucial in TWIST-induced maintenance of mammosphere enrichment and self-renewal capacity, this finding is similar to the tumorigenicity of breast cancer cells in vivo." (PMID 29299179, 2017). "In addition, we observed copy losses of the negative regulators SUFU, as well as of the tumor suppressor WWOX, a newly identified negative modulator of GLI1 in breast cancer." (PMID 27095580, 2016). "In this study, we present in vitro data using a panel of different breast cancer cell lines and demonstrate the modulatory effect of TAM on cellular proliferation and expression of Hedgehog signaling components, including the terminal effector of the pathway, the transcription factor GLI1." (PMID 26927093, 2016). "In addition to SMO inhibitors like vismodegib and sonidegib, which are in clinical use for basal cell carcinoma, GLI1 inhibitors like GANT58 and GANT61 are in preclinical drug development and might be an effective mechanism to overcome drug resistance in breast cancer." (PMID 31394751, 2019). "Moreover, we reported PR, ER and HER-2 were not correlated with Gli1 expression in breast cancer." (PMID 29113369, 2017). "Thus overexpression of GLI1 may not be a general characteristic of all human breast cancers although it could be a useful marker for a subset of human breast tumours, what we will analyse in more detail in our upcoming studies." (PMID 19706168, 2009). "The database analysis of the Hedgehog pathway markers (SHH, PTCH1, SMO, GLI1, and GLI2) revealed that the Hedgehog pathway is activated in breast cancer tissues, and its high expression is not conducive to a patient’s survival." (PMID 36142286, 2022). "Other studies reported that the non-canonical activation of GLI1 by the inflammatory cytokine osteopontin or hypoxia results in the induction of EMT, drug resistance, and invasion capabilities in breast cancer cell lines." (PMID 28974015, 2017). "As GLI1 has been observed to promote cell migration and invasion in other cancer cell types, including non-IBC breast cancer cell lines, we were interested to determine if it has a role in the invasive potential of SUM149 and rSUM149 cells." (PMID 21505458, 2011). "Moreover, GLI1 expression in HR negative breast cancer is predictive of a poor outcome, and GLI 1 knock out breast cancer cells demonstrate reduced viability." (PMID 31394751, 2019). "In vitro studies of Gli-1 have shown high levels of expression in SUM145 cells, which are basal type B as well as triple negative, yet it was not increased in other triple negative and basal-like breast cancer lines, including MDA-MB-231." (PMID 26389956, 2015). "We identified non-canonical NFκB activation of GLI1 in these cells, indicating crosstalk between GLI1 signaling and NFκB pathways in claudin-low and EMT breast cancer cells and suggesting a therapeutic route for claudin-low breast cancer." (PMID 25252859, 2014).
breast carcinoma (continued). "In breast cancer cell lines, OPN induced mesenchymal phenotype by the upregulation and downregulation of several mesenchymal (N-cadherin, vimentin, TWIST, and SLUG) and epithelial (E-cadherin and keratin-18) markers, respectively, through noncanonical regulation of GLI1 (discussed in Section 3.5)." (PMID 34638233, 2021).
medulloblastoma (132 papers, 2010 to 2026). A malignant, invasive embryonal neoplasm arising from the cerebellum. "Evidence from medulloblastoma and basal cell carcinoma indicates that resistance to Smo inhibitors often arises due to downstream mutations or alternative Gli1/2 activation." (PMID 41439992, 2025). "Aberrant activation of GLI1 is indeed associated with numerous human cancers, including glioma, medulloblastoma (MB), osteosarcoma, rhabdomyosarcoma and colorectal cancer." (PMID 39695131, 2024). "In patients with Hh-positive medulloblastomas, five out of ten patients showed an objective response (OR), including four CRs and one PR, associated with elevated GLI1 signature." (PMID 34572373, 2021). "Perturbation of Hh signaling and activation of GLI1 (glioma-associated oncogene 1), a dedicated transcription factor for Hh pathway, are highly associated with several cancers, such as medulloblastoma and basal cell carcinoma." (PMID 29662197, 2018). "Robust single-agent efficacies have also been seen in medulloblastomas, where nearly one-third of cases are associated with constitutive activation of the Gli1 transcription factor through similar oncogenic mutations in the Hedgehog pathway." (PMID 24223768, 2013). "Furthermore, pathway enrichment analysis indicates that GLI1 expression is significantly associated with the “PI3K-AKT signalling pathway” in medulloblastoma." (PMID 31492956, 2019). "Loss of Numb has been described in medulloblastoma, where its downregulation has been associated with the hyperactivation of HH signaling that occurs as a consequence of GLI1 accumulation, leading to in vitro transformation and enhanced tumor growth and metastasis." (PMID 31244888, 2019). "Indeed, MEKK1 overexpression strongly decreases transcriptional activity of GLI1, causing the inhibition of HH-GLI signaling and reduction of cell growth and viability of medulloblastoma cells." (PMID 31244888, 2019). "The group tackle this problem by nanoformulating HPI-1 (NanoHHI) that is a strong antagonist of Gli1 and found that NanoHHI strikingly inhibits the growth of mouse medulloblastoma allografts, which shelter a SmoD477G-binding site mutation, together with substantial downregulation of Gli1 mRNA." (PMID 27148051, 2016). "Analysis of GLI1 protein expression in SUFU-positive and SUFU-deficient human medulloblastoma cells and Sufu knockout mouse embryonic fibroblasts further corroborated the potent activity of DYRKi to inhibit GLI activity in SMO-inhibitor sensitive and resistant cells." (PMID 26784250, 2016). "The group addressed this issue by nanoformulating HPI-1 (NanoHHI) that is a potent antagonist of Gli1 and reported that NanoHHI markedly inhibits the growth of mouse medulloblastoma allografts, which harbor a SmoD477G-binding site mutation, accompanied by significant downregulation of Gli1 mRNA." (PMID 26619402, 2015). "In medulloblastoma, this mechanism of Gli1 regulation also exists, and mutation of these three phosphorylation sites may prevent phosphorylation by AMPK and leads to increased GLI1 protein stability, transcriptional activity, and oncogenic ability." (PMID 26343727, 2015). "Importantly, DYRK1B targeting abolished GLI1 expression in SMO-inhibitor sensitive and SMO-inhibitor resistant cells including SUFU deficient medulloblastoma, GLI1-dependent pancreatic cancer and Ewing sarcoma cells expressing GLI1 in response to the EWS-FLI1 oncoprotein." (PMID 26784250, 2016).
medulloblastoma (continued). "Specifically, AMPK has been shown to phosphorylate and destabilize GLI1, thereby inhibiting its carcinogenic activity in medulloblastoma." (PMID 40063597, 2025). "Upregulation of GLI1 of has previously been reported in sonic hedgehog (SHH) driven medulloblastoma and basal cell carcinoma (BCC)." (PMID 38307877, 2024). "Aberrant activation of sonic hedgehog (SHH) signaling and its effector transcriptional factor GLI1 are essential for oncogenesis of SHH-dependent medulloblastoma (MBSHH) and basal cell carcinoma (BCC)." (PMID 38307877, 2024). "In particular, the DYRKi inhibitor efficiently repressed SMO-dependent Gli1 and SMO-independent Gli1 expression in human medulloblastoma cells (DAOY)." (PMID 38675189, 2024). "For instance, AMPK is capable of directly phosphorylating and destabilizing GLI1 protein, thereby blocking GLI1 transcriptional activity in medulloblastoma." (PMID 36769284, 2023). "And our results confirmed the potential ability of BDDD-721 for therapeutic applications on medulloblastoma via Shh/Gli1 signaling pathway." (PMID 35802536, 2022). "CK-2 inhibition has been shown to reduce GLI1 expression and Hh pathway overactivation in many tumors, including lung cancer, lung cancer cell lines, and medulloblastoma." (PMID 35954384, 2022). "Elevated NADH levels promote the association between the redox sensor CtBP2 and the transcription factor GLI1, leading to inhibition of Hedgehog-dependent transcriptional output and medulloblastoma growth." (PMID 35804992, 2022). "In conclusion, these results indicate that curcumin analogue BDDD-721 has more potent anticancer effects than curcumin on medulloblastomas by targeting Shh/Gli1 signaling pathway." (PMID 35802536, 2022). "Surprisingly, there are also studies reporting that the upstream members of the MAPK cascade, the mitogen-activated kinases MEKK1 and MEKK2/3, can negatively regulate GLI1 in medulloblastoma cells." (PMID 36139698, 2022). "A D473H SMO mutant was also found to confer resistance to vismodegib in a medulloblastoma patient and induced GLI1 luciferase reporter activity in C3H10T1/2 cells." (PMID 34572373, 2021). "Of note, knockdown of CSNK1D was sufficient to reduce HH target gene and GLI1 protein expression in Daoy medulloblastoma cells, suggesting that CSNK1D is required for canonical HH signaling and HH target gene activation." (PMID 34439381, 2021). "PTCH1 LOH has been associated with enhanced medulloblastoma formation as a result of increased SMO and GLI activation, and the loss of GLI1 markedly suppressed spontaneous medulloblastoma formation in Ptc1+/− mice." (PMID 34572373, 2021). "GLI1 was discovered in human glioma, and its signaling pathways have been reported in medulloblastoma and rhabdomyosarcoma." (PMID 33494284, 2021). "4E-BP1-mediated regulation of GLI1 has recently been demonstrated in cerebellar and medulloblastoma growth in mice." (PMID 33081032, 2020). "Together, these data indicate a correlation between PIK3CA expression and GLI1 in medulloblastoma and raise the possibility of a functional relationship between PI3Kα signalling and the GLI1 transcription factor in HH driven cancers." (PMID 31492956, 2019). "Brd4 controls expression of the medulloblastoma essential gene MYC in G3 medulloblastomas, which have poor prognosis as well as GLI1 and GLI2 levels in Sonic hedgehog (SHH)-driven medulloblastomas, which have intermediate prognosis." (PMID 31292434, 2019). "We examined the effects of PI3Kα and mTOR inhibition on GLI1 nuclear accumulation in SHH-driven medulloblastoma using nuclear/cytoplasmic fractionation of DAOY cells with Lamin A/C and tubulin as nuclear and cytoplasmic loading controls, respectively." (PMID 31492956, 2019). "We found dual PI3Kα and mTOR inhibition strongly reduced the amount of nuclear GLI1 protein in HH-driven medulloblastoma and similar results were observed in Ewing sarcoma, another HH-driven paediatric cancer." (PMID 31492956, 2019).